SLIT2 (slit guidance ligand 2)
Diseases named in the same sentence as SLIT2 in open-access papers (continued):
Sharing a sentence is not in itself a finding about the gene and the disease.
thyroid cancer (5 papers, 2023 to 2024). "Further studies demonstrated that Slit2 regulated Hif-1α expression to affect thyroid cancer cells; however, inhibition of miR-200b-3p targeting and downregulation of Slit2 improved hypoxia-ischemic brain damage." (PMID 37097589, 2023).
schizophrenia (4 papers, 2017 to 2025). A major psychotic disorder characterized by abnormalities in the perception or expression of reality. "Mutations in the ROBO3 receptor are associated with axon midline crossing defects in the hindbrain, in patients with horizontal gaze palsy with progressive scoliosis (HGPPS) while de novo mutations in SLIT2/3 are identified in schizophrenia patients." (PMID 37941606, 2023). "There was a highly significant set=level association with schizophrenia (P = 6.31 × 10−9), with 21 genes individually associated at P < 0.05 including BHLHE22 but not SLIT1 or SLIT2." (PMID 39133845, 2024).
small cell lung carcinoma (4 papers, 2004 to 2024). Small cell lung cancer (SCLC) is a highly aggressive malignant neoplasm, accounting for 10-15% of lung cancer cases, characterized byrapid growth, and early metastasis. "In small cell lung cancer (SCLC), the Slit2/Robo1 signaling pathway inhibits the polarization of M2-like macrophages in the TME by suppressing the TGF-β1 signaling pathway." (PMID 39144141, 2024).
squamous cell carcinoma (4 papers, 2011 to 2023). A carcinoma arising from squamous epithelial cells. "Hypermethylation of three CpGs (cg13261825, cg03260566 and cg01663016) in SLIT1, SLIT2 and SLIT3 genes was found at a higher prevalence in adenocarcinoma than in squamous cell carcinoma, although the difference was not statistically significant." (PMID 35053460, 2022).
Anxiety (3 papers, 2020 to 2025). Intense feelings of nervousness, tension, or panic often arise in response to interpersonal stresses. "The hyperactivity of Slit2-Tg mice was observed in the tail suspension test, possibly due to anxiety." (PMID 33613201, 2020). "The anxiety-like behaviors were found in Slit2-Tg mice in the open field test, as well as increased locomotor activity." (PMID 33613201, 2020). "The 21-week-old Slit2-Tg mice exhibited hyperactivity, which may also be due to lower body weight or anxiety." (PMID 33613201, 2020). "The anxiety-like behaviors were also found in adult Slit2-Tg mice in the elevated plus maze." (PMID 33613201, 2020).
bladder urothelial carcinoma (3 papers, 2011 to 2020). "Several studies have showed that SLIT2, a tumor suppressor gene, is epigenetically silenced by hypermethylation of the promoter region in many tumors, and recently in bladder urothelial carcinoma." (PMID 27586786, 2016). "This work identified that the tumor suppressor gene, SLIT2, which inhibited tumor growth and metastasis, was found inactivated by promoter hypermethylation in bladder urothelial carcinoma as well." (PMID 22140553, 2011). "Hypermethylated in cancer 1 (HIC1) and slit homolog 2 (SLIT2) were identified as having differentially up-regulated methylation status of their promoter regions and dramatically down-regulated expression level across all the bladder urothelial carcinoma tissue samples." (PMID 22140553, 2011).
cervical tumors (3 papers, 2012 to 2020). "Several human genes that encode functional inhibitors of the Wnt pathway have been reported to be methylated in cervical tumors including WIF1, CDH1, FHIT, APC, the SLIT2/ROBO family and the SRFP family." (PMID 25826459, 2015). "Microsatellite size alterations (MA) of ROBO1 and SLIT2 were infrequent in cervical tumors, unlike HNSCC." (PMID 22719878, 2012).
diabetic retinopathy (3 papers, 2011 to 2022). "Studies have shown that Slit-2 is expressed in the fibrous vascular membrane of diabetic patients, and Slit-2/Robo1 signaling has been proved to contribute to the development of diabetic retinopathy." (PMID 35813663, 2022). "In this study, we used streptozotocin (STZ)-induced diabetes in the rat to evaluate the expression of Slit2 and its receptor, Robo1, in background diabetic retinopathy." (PMID 28973045, 2017). "The alteration of Slit2 and Robo1 expression in the retinas of diabetic rats and patients with proliferative diabetic retinopathy suggests a role for the Slit-Robo signal in the various stages diabetic retinopathy." (PMID 28973045, 2017).
emphysema (3 papers, 2020 to 2022). "Our findings suggest for the first time that Slit2 may have potential as a therapeutic drug candidate for the treatment of emphysema-associated lung regeneration." (PMID 34035465, 2021). "On the other hand, considering that Slit is also present in the lungs, based on the in vitro results, we aimed to confirm whether Slit2 could act on emphysema-associated lung regeneration." (PMID 34035465, 2021). "When the mouse emphysema model was induced with elastase and intranasally administered Slit2, the therapeutic effects on the repair of alveolar damage were shown." (PMID 34035465, 2021). "Our results also showed that Slit2 administration improved alveolar regeneration in the emphysema mouse model in vivo." (PMID 34035465, 2021). "In the elastase-induced emphysema mouse model, intranasal administration of Slit2 showed therapeutic effects on the regeneration of alveolar destruction." (PMID 34035465, 2021). "Histological analysis and measurement of lung emphysema severity with mean linear intercepts (MLIs) showed that intranasal administration of Slit2 improved lung alveolar regeneration in the emphysema mouse model." (PMID 34035465, 2021). "In this study, we evaluated the effect of Slit2 on the proliferation and migration of mouse lung epithelial cells and its role in regeneration in an emphysema lung mouse model." (PMID 34035465, 2021). "Here, we have shown that Slit2/Robo signaling contributes to the regeneration of lungs damaged by emphysema." (PMID 34035465, 2021). "In this study, we examined the regenerative effect of Slit2 on cell proliferation and migration and an elastase-induced emphysema mouse model." (PMID 34035465, 2021). "After inducing emphysema with elastase, mice were treated by daily intranasal administration of Slit2 from days 7–13." (PMID 34035465, 2021). "In particular, NME1 was reported increased by cigarette smoking in oral squamous cell carcinoma (OSCC), and the lower expression of SLIT2 were found in the lungs of cigarette smoke-induced emphysema mice." (PMID 32795291, 2020). "A protein called Slit2 may help in treating emphysema by promoting regeneration of cells that line the tiny air sacs called alveoli in the lungs." (PMID 34035465, 2021). "Our findings suggest that Slit2 administration may be beneficial for alveolar regeneration in lungs damaged by emphysema." (PMID 34035465, 2021). "We confirmed that Slit2 is involved in MLE-12 cell proliferation and migration in vitro, and we tested the hypothesis that Slit2 plays a role in lung regeneration in the elastase-induced emphysema mouse model." (PMID 34035465, 2021).
ischemic stroke (3 papers, 2020 to 2024). A stroke disorder caused by obstruction of blood flow to the brain, due to thrombotic (local blood clot formation) or embolic (due to a blood clot or other material traveling from another site) event. "In transgenic mice overexpressing human Slit2 (Slit2-Tg), cognition was improved via accelerating glymphatic clearance after ischemic stroke." (PMID 34819849, 2021). "For example, Slit2 levels in the brain increase following ischemic injury, and Slit2 is a crucial element in glial scar formation and brain remodeling in response to ischemic stroke." (PMID 32292352, 2020). "The expressions of endogenous Slit2 and its receptor Robo can be stimulated after cerebral ischemia/reperfusion, suggesting that the Slit/Robo pathway regulates endothelial cell migration, pathological angiogenesis, and vascular integrity during ischemic stroke 13,22." (PMID 39239546, 2024).
lung squamous cell carcinoma (3 papers, 2013 to 2017). "In a previous study, SLIT2 methylation was examined by genome-wide DNA methylation analysis, using a microarray, in squamous cell carcinoma of the lung." (PMID 23381221, 2013). "A recent genome-wide analysis of DNA methylation and gene expression changes in lung squamous cell carcinoma identified several methylation-driven genes, including CCDC37, CYTL1, CDO1, SLIT2, LMO3 and SERPINB538." (PMID 28198450, 2017). "Additionally, we also compared the levels of miR-218, SLIT2 and SLIT3 in lung squamous cell carcinoma subtype and normal tissues." (PMID 28830450, 2017).
malignant glioma (3 papers, 2016 to 2023). A grade III or grade IV glioma arising from the central nervous system. "SLIT2 induces migration of ROBO1/2 (Roundabout1/2) receptor-expressing cells, and in malignant gliomas, SLIT2 expression increases with malignancy." (PMID 37700840, 2023). "Thus, molecules that are generally associated to repulsive clues, such as Slit2–3 and Shh, appeared to be downregulated, whereas attractors such as Wnt7b and Vegfa were upregulated, consistently with the acquisition of the infiltrating capacity that characterizes malignant gliomas." (PMID 26923714, 2016).
meningioma (3 papers, 2014 to 2025). A generally slow growing tumor attached to the dura mater. "The few studies that have directly assessed VS and meningioma indicate similarities in NF2 gene pathogenic variants and in gene expression related to angiogenesis and tumour suppression (PDGFD, CDH1 and SLIT2)." (PMID 41437121, 2025). "Meningioma expressed antigen six ablation in Purkinje cells reduces Slit2 expression and thereby impairs the self-avoidance of Purkinje cell dendrites." (PMID 33718348, 2020). "DEG analysis identified 250 and 68 significantly overexpressed genes in the VS and meningioma tumour samples respectively compared to their control tissues, including six significantly co-overexpressed genes: COL1A, ERBB2, SLFN12, SLIT2, PDGFD and CDH1." (PMID 41437121, 2025).
Sepsis (3 papers, 2016 to 2024). Sepsis is defined as life-threatening organ dysfunction caused by a dysregulated host response to infection. "During systemic infection producing sepsis, vascular leak may occur, and SLIT2 may influence these changes in the vascular integrity." (PMID 32807784, 2020). "Sepsis-induced endothelial activation and injury is mediated in part by the Slit2-Robo4 pathway." (PMID 27890015, 2016).
Wilms' tumours (3 papers, 2004 to 2012). "To investigate the 4p15.2 allelic status of Wilms' tumours with SLIT2 methylation, we typed six methylated tumours for LOH at D4S1546." (PMID 14735202, 2004). "Recently, we reported frequent CASP8 (43%) and RASSF1A (56%) promoter methylation in Wilms' tumours and the present study has demonstrated that SLIT2 methylation represents a further frequent epigenetic change in Wilms' tumours." (PMID 14735202, 2004). "To date, we have not identified an association between CASP8, RASSF1A and SLIT2 methylation in individual tumours, so there is little evidence of a methylator phenotype in a subset of Wilms' tumours." (PMID 14735202, 2004). "In total, 38% (14 out of 37) Wilms' tumours demonstrated SLIT2 CpG island promoter methylation." (PMID 14735202, 2004). "Although p16INK4a(CDKN2a) promoter methylation has been reported in advanced stage Wilms' tumours, this trend was not significant in our series, and to date no specific clinicopathological features have been associated with SLIT2, CASP8 and RASSF1A methylation." (PMID 14735202, 2004).
acute promyelocytic leukemia (2 papers, 2020 to 2024). An aggressive form of acute myeloid leukemia (AML), characterized by arrest of leukocyte differentiation at the promyelocyte stage, due to a specific chromosomal translocation t(15;17) in myeloid cells. "Although the Promyelocytic Leukemia (PML) protein can regulate SLIT2 expression in the central nervous system, little is known about SLIT2 in acute promyelocytic leukemia." (PMID 33120864, 2020). "Here, we aim to assess retrospectively the clinical relevance of the SLIT2 gene in acute promyelocytic leukemia, a homogenous subtype of AML." (PMID 33120864, 2020). "Hence, we aimed to investigate the levels of SLIT2 in acute promyelocytic leukemia (APL) and assess its biological activity in vitro and in vivo." (PMID 33120864, 2020). "To evaluate the impact of SLIT2 levels on clinical and laboratory characteristics, we dichotomized our APL patients from the International Consortium of Acute Promyelocytic Leukemia (IC-APL) cohort (IC-APL, n = 94) into low and high SLIT2 expression using the first quartile (p25) value." (PMID 33120864, 2020).
adenoma (2 papers, 2013 to 2019). A neoplasm arising from the epithelium. "Loss of expression of SLIT2 by promoter hypermethylation and loss of heterozygosity events is significantly associated with serrated adenoma development, and SLIT2 may represent a epimutated tumour suppressor gene according to the Knudson “two hit” hypothesis." (PMID 23671423, 2013). "Our work observed the serum levels of Slit2 in ApcMin/+ mice at the proliferative stage, adenoma stage, and carcinoma stage, and found that the concentration of Slit2 was increased in the serum of all development stages compared with that in wildtype mice." (PMID 31242633, 2019). "We were also reassured by the lack of methylation observed in both normal mucosa and classical adenoma samples, and the fact there was no long range methylation of SLIT2 outside the identified region." (PMID 23671423, 2013). "This study is the first to demonstrate SLIT2 LOH, promoter methylation and down-regulation consistently occurring in a pre-malignant lesion (the sessile serrated adenoma), and may explain partially the alternate pathway by which sessile serrated adenomas progress towards carcinoma." (PMID 23671423, 2013).
asthma (2 papers, 2013 to 2021). "detected decreased levels of ROBO2 and SLIT2 in chronic obstructive pulmonary disease (COPD) patients, a disease with underlying mechanisms shared with asthma." (PMID 34442380, 2021).
bowel cancer (2 papers, 2015 to 2023). "The fact that activation of Slit2/Robo1 signaling led to an altered epithelial structure in our study further demonstrates that Slit2 can drive the precancerous lesions of the intestine to intestinal cancers." (PMID 25605242, 2015). "These two models can mimic the process of in vivo intestinal tumorigenesis, and allow us to successfully define the expression and function of Slit2/Robo1 signaling during the tumorigenesis and progression of the intestinal cancers." (PMID 25605242, 2015). "We have demonstrated that Slit2 was overexpressed in the early-stage intestinal tumors with its expression progressively increased during the development of intestinal cancer." (PMID 25605242, 2015). "This study has clearly demonstrated an oncogenic role of Slit2/Robo1 signaling during the tumorigenesis and progression of intestinal cancer." (PMID 25605242, 2015). "In summary, our data have demonstrated that activation of Slit2/Robo1 signaling is critically involved in the intestinal tumorigenesis and Slit2 may constitute a potential biomarker for the early detection and therapy of intestinal cancers." (PMID 25605242, 2015). "The SLIT2/ROBO1 pathway has been shown to be involved in the progression of intrahepatic cholangiocarcinoma (ICC), breast and bowel cancer." (PMID 37059586, 2023).
Cerebral ischemia (2 papers, 2019 to 2024). Restriction of arterial blood supply to the brain associated with insufficient oxygenation to support the metabolic requirements of the tissue. "Based on its anti-inflammatory role, Slit2 has been implicated as an effective neuroprotector against global cerebral ischemia by stabilizing the blood–brain barrier during a surgical brain injury." (PMID 30717252, 2019). "Taken together, Slit2 can prevent cerebral ischemia, reduce tissue injury, and promote tissue recovery after cerebral ischemia." (PMID 39239546, 2024).
cholangiocarcinoma (2 papers, 2022 to 2023). A carcinoma that arises from the intrahepatic biliary tree (intrahepatic cholangiocarcinoma) or from the junction, or adjacent to the junction, of the right and left hepatic ducts (hilar cholangiocarcinoma). "Recently, inactivating mutations in SLIT2 and ROBO1 were identified in a subset of relapsing cholangiocarcinoma patients." (PMID 37311584, 2023).
chronic obstructive pulmonary disease (2 papers, 2013 to 2021). A chronic and progressive lung disorder characterized by the loss of elasticity of the bronchial tree and the air sacs, destruction of the air sacs wall, thickening of the bronchial wall, and mucous accumulation in the bronchial tree. "The methylation level of SLIT2 was significantly higher in cases of chronic obstructive pulmonary disease (COPD) when compared with the level in non-COPD cases (P=0.05)." (PMID 23381221, 2013).
cognition impairment (2 papers, 2020). "Our results strongly suggest that overexpression of Slit2 protected against the dysfunction in MIs, which is a potential therapeutic target for cognition impairment in the elderly." (PMID 33028376, 2020).
colitis (2 papers, 2020 to 2024). Inflammation of the colon. "Based on the GEO analysis, we next investigated whether Slit2/Robo1 signaling affects DSS-induced colitis in Slit2-Tg and Robo1/2 +/- mice." (PMID 32398956, 2020). "Robo1, the receptor for the secreted glycoprotein Slit2, mediates DSS-induced colitis by activating the autophagy of Lgr5+ ISCs." (PMID 38891118, 2024).
diabetes (2 papers, 2017 to 2024). "At 6 months after diabetes induction, both the Slit2 and the Robo1 expression patterns remained the same as at 3 months, with the exception that expression in the outer nuclear layer was decreased." (PMID 28973045, 2017). "Our study examined the expression of Slit2 and its receptor, Robo1, in a rat model of streptozotocin-induced diabetes and in patients with proliferative diabetic retinopathy." (PMID 28973045, 2017). "The findings of this study indicate that STZ-induced diabetes in rats resulted in the time-dependent alteration of the expression of both Slit2 and Robo1 in retinal tissue." (PMID 28973045, 2017).
esophageal squamous cell carcinoma (2 papers, 2015 to 2022). Esophageal squamous cell carcinoma (ESCC) is a type of esophageal carcinoma (EC) that can affect any part of the esophagus, but is usually located in the upper or middle third. "Knockdown of SLIT2 increases migration of esophageal squamous cells, and low expression of SLIT2 protein is correlated with poor overall survival and disease-free survival in esophageal squamous cell carcinoma." (PMID 35053460, 2022). "In esophageal cancers, SLIT2 is a migration suppressor for ESCC (esophageal squamous cell carcinoma) via inhibition of srGAP–Cdc42 signaling and membrane localization of p-FAK and p-Paxillin." (PMID 26674478, 2015).
fibrosis (2 papers, 2021 to 2023). the formation of excess fibrous connective tissue in an organ or tissue in a reparative or reactive process. "For its protective role in bleomycin induced fibrosis, we considered the age-dependent repression of slit guidance ligand 2 as detrimental." (PMID 37932771, 2023). "A further correlation analysis revealed that SLIT2 and CXCL6 owned high positive correlation coefficients with fibrosis grade, while the proportion of resting NK cells was negatively correlated." (PMID 35111704, 2021).